IL22 (interleukin 22)
Diseases named in the same sentence as IL22 in open-access papers (continued):
Sharing a sentence is not in itself a finding about the gene and the disease.
intestinal tumors (4 papers, 2015 to 2025). "In some cases, overexpression of IL-22 is associated with the progression of intestinal tumors, while in other cases, it may inhibit tumorigenesis by promoting epithelial cell repair and regeneration." (PMID 41019044, 2025). "However, deficiency in Il22 leads to delayed wound healing and increased inflammation and therefore promotes intestinal tumor development in the AOM/DSS model of CAC." (PMID 27148488, 2016). "Similarly, in a model of epithelial tumorigenesis, IL-22 induction at baseline is protective, whereas sustained high levels of IL-22 cause prolonged epithelial proliferation promoting intestinal tumours." (PMID 25860963, 2015). "IL-7 was recently identified as a cytokine produced by macrophages in response to fungal stimulation, which increased the expression of Stat3 and AhR in ILC3 to enhance IL‐22 production, eventually promoting the formation of intestinal tumors." (PMID 37122757, 2023). "In Helicobacter hepaticus/AOM-induced intestinal tumors, IL-22 released by ILCs supported the growth of intestinal tumors in T and B cell-deficient Rag2−/− mice." (PMID 27148488, 2016). "Even though IL-22 is known for its protective effects on intestinal health, its contribution to the progression of intestinal tumors may be exploited by tumor cells, thereby promoting tumor growth and metastasis." (PMID 41019044, 2025). "Because IL-22 also mediates intestinal epithelial tissue regeneration, it is speculated that its overexpression or dysregulation may be responsible for the development of intestinal tumors." (PMID 37122757, 2023).
ischemic stroke (4 papers, 2021 to 2022). A stroke disorder caused by obstruction of blood flow to the brain, due to thrombotic (local blood clot formation) or embolic (due to a blood clot or other material traveling from another site) event. "Our data indicate that IL-22 may serve as an attractive therapeutic target for treating ischemic stroke and cerebral I/R injury." (PMID 33790691, 2021). "However, it remains unclear whether IL-22 is involved in ischemic stroke and cerebral I/R injury." (PMID 33790691, 2021). "However, the effects of IL-22 on ischemic stroke and cerebral I/R injury remain unclear." (PMID 33790691, 2021).
keloid (4 papers, 2020 to 2025). An irregularly shaped, elevated mark on the skin caused by deposits of excessive amounts of collagen during wound healing. "On the other hand, pathologic scarring is also a consequence of IL-22 expression, with high levels of these cytokine being identified in keloid scars." (PMID 35409053, 2022). "Only IL-22, transforming growth factor-β, and arginase-1 exhibited significant higher levels in keloid scars." (PMID 35409053, 2022). "The number of relative copies of IL-22 mRNA was significantly higher in patients with keloids." (PMID 39799030, 2025). "Another article reported a significantly higher local expression of IL-22 mRNA in keloid scars." (PMID 35409053, 2022). "However, overexpression of IL-22 can cause negative effects, such as keloid scars or peritoneal adhesions." (PMID 35409053, 2022). "Only IL-22, TGF-β, and arginase-1 exhibited significantly higher levels in keloid scars." (PMID 39799030, 2025). "Biopsies from normal and keloid scars were collected and the mRNA expression of several growth factors and cytokines were determined: TGF-β, fibroblast growth factor, IL-33, IL-22, arginase-1, arginase-2, inducible nitric oxide synthase, vasoactive intestinal peptide, and its receptor." (PMID 39799030, 2025). "In addition, the factors related to Th1, Th2, and Th17 cells such as IL4/IL13, IL17A/IL22, ADAM33, IFN-γwere upregulated overall in keloid and AD." (PMID 38476235, 2024).
lung adenocarcinoma (4 papers, 2015 to 2023). A carcinoma that arises from the lung and is characterized by the presence of malignant glandular epithelial cells. "Serum IL-22 concentration was comparable between NCs and lung adenocarcinoma patients (78.27 ± 12.47 compared with 79.78 ± 10.96 pg/ml, P=0.686)." (PMID 30473538, 2018). "The bioactivity (including cellular proliferation, cell cycle, apoptosis, and invasion) of lung adenocarcinoma cell line A549 was also assessed in response to recombinant IL-22 stimulation in vitro." (PMID 30473538, 2018). "The current data indicated that elevated Notch1 induced higher IL-22 secretion by CD4+ T cells in lung adenocarcinoma patients, and Notch-AhR-IL-22 axis took part in the pathogenesis of lung adenocarcinoma." (PMID 30473538, 2018). "Due to the potential context-dependent protective and promotional effects of IL-22 during tumor formation and progression, we examined which function of IL-22 might predominate in lung adenocarcinoma cell line by in vitro stimulation." (PMID 30473538, 2018). "In vitro IL-22 stimulation promoted the invasion of lung adenocarcinoma cell line A549 cells." (PMID 30473538, 2018). "Thus, the current data suggested that IL-22 might directly promote lung adenocarcinoma growth by engaging STAT3 signaling." (PMID 30473538, 2018). "In this study, we also revealed down-regulation of IL-22 secretion and AhR mRNA expression, but comparable RORγt mRNA level, in lung-resident CD4+ T cells in response to Notch signaling inhibition in lung adenocarcinoma patients." (PMID 30473538, 2018). "In conclusion, elevated Notch1 induced higher IL-22 secretion by CD4+ T cells in lung adenocarcinoma patients, and Notch-AhR-IL-22 axis took part in the pathogenesis of lung adenocarcinoma." (PMID 30473538, 2018). "In contrast, IL-22 expression in BALF was significantly elevated in tumor site (271.1 ± 67.38 pg/ml) compared within nontumor site (68.67 ± 16.39 pg/ml, P<0.0001) in lung adenocarcinoma patients." (PMID 30473538, 2018). "Thus, we further showed that IL-22 expression (protein and mRNA) in CD4+ T cells from tumor site was elevated than those from nontumor site, indicating that elevated IL-22 expression in BALF might be due to the increased production by CD4+ T cells, not lung adenocarcinoma cells." (PMID 30473538, 2018).
melanoma (4 papers, 2007 to 2021). A malignant, usually aggressive tumor composed of atypical, neoplastic melanocytes. "On the other hand, the number of IL-22+ TILs from the melanoma samples was higher than that of the PBMC (1.8% ± 0.3) and analogous to the number of IL-22+ TILs isolated from BCC samples (9.6% ± 1.3)." (PMID 34944746, 2021). "The levels of IL-6, IL-8, IL-10, IL-17A, IL-27, IL-31, GM-CSF, IFN-α, IL-9, VEGF-D, TNF-β, NGFβ, IL-23, IL-22, and IL-1α were below the threshold of detection in both melanoma patients and healthy controls." (PMID 33574842, 2021). "While this suggests that IL-22 may also promote the development and progression of melanoma, further investigation is needed." (PMID 28558005, 2017).
myelodysplastic syndrome (4 papers, 2014 to 2024). A clonal hematopoietic disorder characterized by dysplasia and ineffective hematopoiesis in one or more of the hematopoietic cell lines. "Recent studies show that IL-22 has also been implicated in the etiology of inflammatory and autoimmune diseases, myelodysplastic syndrome (MDS) and T-cell acute lymphoblastic leukemia (T-ALL)." (PMID 24473142, 2014).
nephritis (4 papers, 2018 to 2025). Inflammation of renal tissue. "However, although Il17rc−/− and Il17ra−/− mice developed hyper Th17 cells with elevated Il22 expression and skin inflammation, they did not develop SLE-nephritis and Sjögren’s-like disease." (PMID 30013031, 2018).
non-alcoholic fatty liver disease (4 papers, 2021 to 2025). "In non-alcoholic fatty liver disease (NAFLD) or metabolic dysfunction-associated steatohepatopathy (MASLD), IL-22 exerts protective effects by regulating lipid metabolism and suppressing inflammatory responses." (PMID 41562076, 2025). "Similarly, interleukin-22 (IL-22)-expressing Lactobacillus reuteri obviously decreased the incidence of nonalcoholic fatty liver disease in high-fat diet mice." (PMID 36312915, 2022). "An engineered L. reuteri secreting interleukin -22 was developed based on the probiotic L. reuteri ATCC PTA 6475 and could ameliorate non-alcoholic fatty liver disease." (PMID 36364752, 2022).
oral squamous cell carcinoma (4 papers, 2012 to 2021). "The association of IL‐22 with EMT is also reported in keratinocytes and oral squamous cell carcinomas where it suppresses differentiation‐related factors in cells and renders them more susceptible to oncogenic transformation." (PMID 31725949, 2020). "We examined IL-22 signal transduction in oral squamous cell carcinoma (OSCC) cells." (PMID 22922995, 2012). "Using confocal microscopy, we confirmed IL-22-induces P-STAT3 nuclear accumulation and STAT3 nuclear translocation, as recently described in oral squamous cell carcinoma." (PMID 25793261, 2015).
pertussis (4 papers, 2022 to 2025). A contagious bacterial respiratory infection caused by Bordetella pertussis. "By simultaneously eliciting potent systemic and mucosal immunity, including TRM induction and IL-22–mediated mucosal defense, this strategy offers a feasible and strategically sound approach to strengthen global pertussis control and reduce transmission." (PMID 40963598, 2025). "At this time point, BAFF and IL-33 were associated with higher 12-month pertussis IgG levels, and APRIL and IL-22 were associated with tetanus." (PMID 37251388, 2023). "However, IL-22 has been detected in the blood of individuals who received a booster dose of whole-cell or acellular pertussis vaccine." (PMID 40612502, 2025). "Th1 and Th17 T-cell responses against pertussis antigens were measured by stimulating peripheral blood mononuclear cells (PBMCs) with either PRN, PT, or FHA for 7 days and measuring secreted IFNγ, IL-22, and IL-17 by ELISA26." (PMID 35177621, 2022).
Pleural effusion (4 papers, 2011 to 2021). The presence of an excessive amount of fluid in the pleural cavity. "Levels of IL-22 in pleural effusion and pericardial effusions from TB patients were readily detectable in most patients." (PMID 21767990, 2011). "IL-22 levels were higher in pericardial effusions compared with pleural effusions (p = 0.04)." (PMID 21767990, 2011). "The frequency of CD4+IL-9+, CD4+IL-17+, CD4+ IL-22+, and CD4+CD25+FOXP3+ cells in the pleural effusions." (PMID 34925358, 2021). "We also checked IL-17A and IL-22 production in MAIT cells by intracellular staining with specific antibodies and flow cytometry, and both of them were minimal in MAIT cells but were clearly detected in other cells from pleural effusions (data not shown)." (PMID 27586092, 2016).
skin infection (4 papers, 2013 to 2025). An inflammatory process affecting the skin, caused by bacteria, viruses, parasites, or fungi. "IL-17A and to a lesser degree, IL-22 have been linked to protection in mouse models of skin infection yet IL-26 remains quite understudied, likely due to its absence in the mouse genome and to the difficulty to reveal it by intracellular cytokine staining." (PMID 39981298, 2024).
staphylococcal infection (4 papers, 2018 to 2025). An infection caused by Staphylococcus. "IL-22 was found to be crucial in cutaneous immunity against staphylococcal infection first through the induction of adenosine monophosphates (AMPs) synthesis and second by influencing T-cell and neutrophil chemotaxis." (PMID 30291393, 2019).
acute liver failure (3 papers, 2013 to 2021). Rapid deterioration of liver function causing encephalopathy and coagulopathy. "The therapeutic efficacy of interleukin-22 (IL-22) on liver injury and hematological disturbances was studied in rat model of acute liver failure (ALF) induced by D-galactosamine/lipopolysaccharide (D-GalN/LPS)." (PMID 24799907, 2014). "The possible hepato-protective effects of IL-22 producing cells may not be exclusively related to alcohol-mediated inflammatory injury, because IL-22 has been suggested to play a protective role in both HBV, HCV and in models of acute liver failure." (PMID 23372820, 2013).
AIDS (3 papers, 2010 to 2023). A syndrome resulting from the acquired deficiency of cellular immunity caused by the human immunodeficiency virus (HIV). "Thus, depletion of either Th17/Th22 cells and other IL-17/IL-22-producing cells such as ILCs results in compromise of mucosal integrity and progression to AIDS." (PMID 25364618, 2014). "However, in diseases such as AIDS, the acute phase proteins mediated by IL-22 are protective." (PMID 36839448, 2023). "Therefore we calculated the Spearman correlation coefficients for plasmatic levels of IL-10, IL-22 and CRP and disease progression as defined by patients' viral load, CD4 cell counts, and AIDS-defining conditions." (PMID 20211031, 2010).
autoimmune myocarditis (3 papers, 2012 to 2025). Autoimmune myocarditis is an autoimmune disease that affects the heart. "However, Both the pathogenic effect of Anti-IL-22 Ab in our AVMC model and protective role of the IL-22-Ig fusion gene in experimental autoimmune myocarditis (EAM) model, suggest that this cytokine has an important myocardium-protective role regardless of the cell source." (PMID 23050732, 2012).
autoimmune thyroid disease (3 papers, 2017 to 2022). Inflammatory disease of the thyroid gland due to autoimmune responses leading to lymphocytic infiltration of the gland. "As there are no previous studies on the interleukin-22 (IL-22) variants in autoimmune thyroid disease (AITD), the present study aimed to explore the association between polymorphisms of IL-22 and the predisposition to AITD." (PMID 28839453, 2017).
B-cell chronic lymphoid leukemia (3 papers, 2017 to 2019). "B-cell cancers, such as B-ALL (B-cell acute lymphoid leukemia) and B-CLL (B-cell chronic lymphoid leukemia) are driven by upregulation of IL-7 and IL-22 which also simulate STAT5B." (PMID 31717342, 2019). "Transcriptomic profiling from chronic lymphocytic leukemia patients successfully treated with CAR-T cells, revealed a general implementation of the IL-6/STAT3 signaling pathways, as indicated by increased production of IL-6, IL-17, IL-22, IL-31 and CCL20." (PMID 30999624, 2019).
bacteremia (3 papers, 2014 to 2021). "Thus, decreased activation of macrophages responsible for producing proinflammatory cytokines is likely contributing to the decreased induction of IL-22 and enhanced bacteremia in JLB12-infected mice." (PMID 29720526, 2018). "Furthermore, IL-22 and surfactant proteins have been shown to be essential for limiting pneumococcal pneumonia, and EF3030 is a pneumococcal strain that does not readily induce bacteremia." (PMID 29720526, 2018).
bladder cancer (3 papers, 2015 to 2023). "In conclusion, to the authors' knowledge, this is the first report documenting that the IL-22 -429 C/T gene polymorphism is associated with bladder cancer risk." (PMID 26598081, 2015). "In this study, we investigated the association between three common polymorphisms (-429 C/T, +1046 T/A and +1995 A/C) of the IL-22 gene and the risk of bladder cancer in a Chinese population." (PMID 26598081, 2015). "This prospective hospital-based case-control study revealed that the IL-22 -429 C/T gene polymorphism is associated with bladder cancer risk." (PMID 26598081, 2015). "The mechanisms of action for the IL-22 -429 TT genotype and T allele as risk factors for bladder cancer are still unclear." (PMID 26598081, 2015). "The aim of this study was to investigate the association between IL-22 gene polymorphisms (-429 C/T, +1046 T/A and +1995 A/C) and the risk of bladder cancer in a Chinese population." (PMID 26598081, 2015). "Antagonistic inhibitors of IL‐17 and IL‐22 need to be investigated in future studies to target Th17‐like hILC1s as novel treatment strategies in bladder cancer." (PMID 34496133, 2021). "When stratifying according to the stage of bladder cancer, we found that patients with superficial bladder cancer had a significantly lower frequency of the IL-22 -429 TT genotype (OR=0.48, 95% CI=0.23, 0.98; p=0.04)." (PMID 26598081, 2015). "The patients with bladder cancer had a significantly higher frequency of the IL-22 -429 TT genotype (OR=2.04, 95% CI=1.19, 3.49; p=0.009) and -429 T allele (OR=1.42, 95% CI=1.08, 1.87; p=0.01) than the healthy control subjects." (PMID 26598081, 2015). "When stratifying according to the stage of bladder cancer, we found that superficial bladder cancer had a significantly lower frequency of the IL-22 -429 TT genotype (OR=0.48, 95% CI=0.23, 0.98; p=0.04)." (PMID 26598081, 2015). "Patients with bladder cancer had a significantly higher frequency of the IL-22 -429 TT genotype [odds ratio (OR)=2.04, 95% confidence interval (CI)=1.19, 3.49; p=0.009] and -429 T allele (OR=1.42, 95% CI=1.08, 1.87; p=0.01) than the healthy controls." (PMID 26598081, 2015). "IL-22 has been identified as a poor prognostic factor in bladder cancer." (PMID 38026978, 2023). "However, the role of IL-22 in bladder cancer has not been investigated." (PMID 26598081, 2015).
bovine tuberculosis (3 papers, 2012 to 2016). "Gene transcription studies have identified dual roles for the cytokines IL-17A and IL-22 in bovine tuberculosis, where they show potential as both predictors of vaccine success and correlates of infection." (PMID 27427303, 2016). "Thus, murine transcriptome analysis can be used to predict immunological responses in cattle allowing the prioritisation of CXCLl9, CXCL10, Granzyme A and IL-22 as potential additional readout systems for the ante-mortem diagnosis of bovine tuberculosis." (PMID 22359547, 2012).
Cachexia (3 papers, 2015 to 2026). Severe weight loss, wasting of muscle, loss of appetite, and general debility related to a chronic disease. "We have previously found that the IL-22TG8, TG9, and TG15 mice had much lower lean body weight, suggesting that super high IL-22 levels may cause cachexia." (PMID 26064446, 2015). "At present, the mechanisms underlying IL-22-mediated cachexia remain unclear." (PMID 26064446, 2015). "Super high levels of IL-22 may cause cachexia and subsequently body weight loss." (PMID 26064446, 2015). "Whereas considerable high concentration of IL-22 probably leads to cachexia and certain relatively high concentration appears to play no role in obese mice." (PMID 37525285, 2023). "It is likely that super high levels of IL-22 promote cachexia by using mechanisms similar to those used by these cytokines such as induction of strong acute phase response and subsequent chronic inflammation." (PMID 26064446, 2015). "High blood levels of IL-22, however, appear to have negative consequences such as cachexia and IR." (PMID 37525285, 2023).
campylobacteriosis (3 papers, 2016 to 2017). Infections with bacteria of the genus campylobacter. "In conclusion, the regulatory pathways within the IL-23/IL-22/IL-18 axis following C. jejuni infection need to be further unraveled in future studies in order to improve our understanding of the distinct molecular mechanisms underlying campylobacteriosis." (PMID 27385977, 2016). "Very recently our group has highlighted the importance of the IL-23/IL-22/IL-18 axis in campylobacteriosis." (PMID 28127403, 2017). "In the present study we dissected the role of cytokines belonging to the IL-23 / IL-22 / IL-18 axis in murine campylobacteriosis." (PMID 27322540, 2016).
chronic liver failure (3 papers, 2021 to 2023). Liver failure that develops slowly and gradually for some time, possibly for years, often as the result of cirrhosis, or malnutrition. "Circulating IL-22 was associated with MELD score and the chronic liver failure consortium (CLIF-C) acute-on-chronic liver failure score (CLIF-C ACLFs)." (PMID 36117587, 2022). "Studies have indicated that the increase in Th22/IL-22 is related to the severity of hepatitis B virus-related chronic liver failure (HBV-ACLF) and suggested that Th22/IL-22 can be used as a biomarker for the prognosis of HBV-ACLF." (PMID 34295334, 2021).